LINC00518 (long independently transcribed non-coding RNA 518)
Synonyms: MGC40222; LENOX; formerly C6orf218
Gene: Long non-coding RNA gene on chromosome 6 (10,423,133 to 10,458,070, reverse strand). Ensembl gene ENSG00000183674.
Diseases named in the same sentence as LINC00518 in open-access papers:
LINC00518 is named in the same sentence as 16 diseases in open-access papers, as found by Europe PMC text mining. Sharing a sentence is not in itself a finding about the gene and the disease. The quoted sentences say what the papers report.
melanoma (15 papers, 2019 to 2025). A malignant, usually aggressive tumor composed of atypical, neoplastic melanocytes. "Notably, high levels of LINC00518 are associated with advanced clinical staging of melanoma, indicating its potential role in the progression of the disease." (PMID 39108268, 2024). "An example of lncRNA primarily located in the cytoplasm and upregulated in melanoma cell lines is LENOX (LINC00518—lincRNA-enhancer of oxidative phosphorylation)." (PMID 40076754, 2025). "LINC00518 (ENSG00000183674), also known as LENOX or C6orf218, was first discovered in 2014 and has since emerged as a highly valuable non-invasive method for distinguishing melanoma from nevi." (PMID 39108268, 2024). "In melanoma, LINC00518 positively regulates EIF5A2 expression by directly binding miR-526–3p, suppressing melanoma (CMM) proliferation and metastasis." (PMID 39108268, 2024). "Reportedly, LINC00518 is significantly overexpressed in melanoma tissues compared to adjacent normal tissues." (PMID 39108268, 2024). "Some researches have been made to demonstrate that, in melanoma, prostate cancer, and breast cancer, LINC00518 plays a similar role." (PMID 35246517, 2022). "Some studies have reported that LINC00518 is highly expressed in melanoma and plays a key role in the malignant progression of melanoma." (PMID 33664256, 2021). "Among these genes was the tumor-specific LINC00518 gene, which has been proposed as a two-gene classifier for melanoma detection, together with the TAA PRAME47." (PMID 32157095, 2020). "Although some studies have reported that LINC00518 is dysregulated in melanoma, the exact function and mechanism of LINC00518 in melanoma are still unclear." (PMID 31712557, 2019). "Supposing that LINC00518 also has the same effect in melanoma, we constructed a LINC00518-miRNA-target gene network using Cytoscape to visualize their interrelationships based on our miRNA-seq and RNA-seq data." (PMID 31712557, 2019). "Lastly, we also showed that LINC00518 also promotes melanoma metastasis in vivo by regulating the expression of AP1S2." (PMID 31712557, 2019). "These revealed that LINC00518 modulates the metastasis of melanoma cells through sponging miR-204-5p to promote AP1S2 expression." (PMID 31712557, 2019). "FISH and qRT-PCR of nucleus and cytoplasm fractions revealed that LINC00518 was mainly localized in cytoplasm in melanoma cells." (PMID 31712557, 2019). "Furthermore, LINC00518 not only promotes tumor growth in melanoma but also increases the number of lung metastatic nodules." (PMID 39108268, 2024). "Additionally, LINC00518 indirectly promotes AP1S2 via miR-204–5p in melanoma, playing a crucial role in disease progression." (PMID 39108268, 2024). "Similarly, melanoma cells can overexpress the lncRNA LENOX (LINC00518) following LENOX genomic amplification or increased activity of SOX10 and TFAP2A." (PMID 36497341, 2022). "Similarly, it was found that LINC00518 promoted the migration, invasion, and metastasis of melanoma through the miR-204-5p/AP1S2 and miR-33a-3p/HIF-1α axes, which is consistent with our finding that LINC00518 serves as a risk factor for SKCM." (PMID 36371574, 2022). "Although it has been reported that LINC00518 is dysregulated in melanoma, its exact role and molecular mechanism in melanoma remain unclear." (PMID 31712557, 2019). "The expression of LINC00518 in melanoma tissues was upregulated 7.67-fold." (PMID 31712557, 2019). "Our results suggest that LINC00518 could promote metastasis in malignant melanoma." (PMID 33664256, 2021). "Malignant melanoma cell (A375, A2058, SK-MEL-28) expressed higher LINC00518 levels compared to human epidermal melanocytes (HEMa-LP)." (PMID 31712557, 2019). "Long intergenic nonprotein coding RNA 518 (LINC00518), has been known to promote and up-regulate cancer cell proliferation and metastasis in cervical cancer, breast cancer, and malignant melanoma." (PMID 35246517, 2022).
melanoma (continued). "LINC00518 expression was higher in metastatic melanoma cell lines (WM451 and A375 cells), and lower in normal melanocytes cell lines (HM) and primary melanoma cell lines (WM35 cells), these melanoma cell lines have shown different metastatic potential." (PMID 33664256, 2021).
breast carcinoma (4 papers, 2019 to 2024). "The upregulation of LINC00518 has been shown to promote the metastasis and in vivo growth of breast cancer." (PMID 39108268, 2024). "Some reports have already suggested an oncogenic role for LINC00518 in several other cancer models, including breast cancer, cervical cancer, prostate cancer, and skin melanoma." (PMID 33371395, 2020). "LINC00518 is notably overexpressed in breast cancer tissues." (PMID 39108268, 2024). "Likewise, in breast cancer, downregulation of LINC00518 impedes Wnt signaling activation, thereby restraining the expression of EMT-associated proteins Slug, Snail1, Twist1, ZEB1, and ZEB2, while promoting E-cadherin expression." (PMID 39108268, 2024). "Therefore, targeting LINC00518 may offer a novel therapeutic approach for overcoming multidrug resistance in breast cancer." (PMID 39108268, 2024).
cervical cancer (3 papers, 2020 to 2024). A primary or metastatic malignant neoplasm involving the cervix. "Specifically, silencing LINC00518 in cervical cancer cells leads to a significant reduction in N-cadherin and vimentin expression while elevating the epithelial marker E-cadherin’s protein levels." (PMID 39108268, 2024). "Therefore, we can confidently conclude that the activation of the JAK/STAT3 signaling pathway regulated by LINC00518 enhances cell growth in cervical cancer." (PMID 39108268, 2024).
lung adenocarcinoma (2 papers, 2022). A carcinoma that arises from the lung and is characterized by the presence of malignant glandular epithelial cells. "For example, LINC00518 is a tumor-promoting factor in multiple tumors, including lung adenocarcinoma, cervical, breast, and non-small cell lung cancer." (PMID 36371574, 2022).
prostate carcinoma (2 papers, 2020). A carcinoma that arises from epithelial cells of the prostate gland. "LINC00518 and LINC00460 act as oncogenes to facilitate tumor progression, including prostate cancer, gastric cancer, colon cancer, and lung cancer." (PMID 33042838, 2020).
metastatic melanoma (1 paper, 2021). A melanoma that has spread from its primary site to another anatomic site. "LINC00518 and LINC00520 were each found to be independent risk factors for metastatic melanoma patient survival and the network motif UCA1/hsa-miR-125b-1/AKT1 has an 88% chance of correctly identifying a TCGA sample as metastatic melanoma." (PMID 35008286, 2021).
sarcoma (1 paper, 2021). A usually aggressive malignant neoplasm of the soft tissue or bone. "Repression of LINC00518 expression using an shLINC00518 plasmid, or Santacruzamate A, reduced the tumorigenic ability of WM451 and A375 cells, and increased their radiosensitivity in the subcutaneous sarcoma model." (PMID 33664256, 2021).
skin melanoma (1 paper, 2020). "The involvement of LINC00518 in metastasization was also reported in other cancer models, including skin melanoma." (PMID 33371395, 2020).
tumor (10 papers, 2013 to 2024). "Elevated levels of LINC00518 in tumor tissues are associated with increased tumor size, advanced clinical stage, metastasis, and poor survival prognosis." (PMID 39108268, 2024). "Understanding the molecular mechanisms underlying LINC00518’s interactions with miRNAs and their downstream targets can provide valuable insights into tumor progression and resistance, offering new avenues for personalized cancer treatment." (PMID 39108268, 2024). "By functioning as a miRNA sponge, LINC00518 regulates the expression of downstream messenger RNAs (mRNAs), thus influencing tumor progression." (PMID 39108268, 2024). "Collectively, these findings underscore the significant involvement of LINC00518 in tumor chemoresistance." (PMID 39108268, 2024). "In summary, LINC00518 promotes tumor cell proliferation, migration, invasion, and clustering by regulating the downstream miR-335–3p-CTHRC1-integrin β3/FAK pathway." (PMID 39108268, 2024). "LINC00518 was found to be highly expressed in many human cancers including gallbladder cancer and colorectal cancer and acted as a functional player in tumor cell proliferation, migration and invasion." (PMID 33937054, 2021). "Furthermore, LINC00518’s overexpression promotes tumor growth in multiple myeloma cells by downregulating miR-140–5p expression and upregulating ATG14 expression." (PMID 39108268, 2024). "These interactions highlight LINC00518’s complex role in tumor biology." (PMID 39108268, 2024). "Moreover, in vivo experiments have shown that Linc00337, Linc00460, Linc00518, Linc00922, Linc01119, and Linc02163 induce tumor growth and metastasis in vivo which suggests that they could be potential targets for developing novel anti-metastatic therapeutics." (PMID 36139687, 2022). "In summary, LINC00518 indirectly regulates HIF-1α, promoting tumor cell proliferation, migration, invasion, and colony formation." (PMID 39108268, 2024). "The LINC00518–HIF-1α–glycolysis axis can promote oncogenesis and the development of CMM cells by allowing CMM cells to adapt to a state of tumor hypoxia." (PMID 33664256, 2021). "In clinical samples, patients with larger tumor size and late pathological stage (TNM stages) have higher LINC00518 levels." (PMID 33937054, 2021). "Knockdown of LINC00518 expression in WM451 and A375 cells decreased glucose consumption, ATP levels, and lactic acid production in the cells, while overexpression of HIF-1α significantly reversed the effects of LINC00518 silencing of glycolytic tumor metabolism in WM451 and A375 cells." (PMID 33664256, 2021). "According to the subsequent bioinformatics analyses and luciferase reporter assays, we predicted that the LINC00518 may have a strong interaction with miR-185-3p.In this study, we first proved that miR-185-3p was down-regulated in LUAD tumor tissues and cell lines." (PMID 33937054, 2021). "Recently, our group reported the increased expression of LINC00518 (long intergenic non-protein coding RNA 518) and LINC00634, now named SMIM45 (small integral membrane protein 45), in a cohort of forty-one UM patients comparing tumor and normal adjacent tissues." (PMID 36765733, 2023).
cancer (6 papers, 2019 to 2025). A tumor composed of atypical neoplastic, often pleomorphic cells that invade other tissues. "The detection of LINC00518 dysregulation associated with several in vitro functional assays allowed us to investigate its ceRNA regulatory network and shed light on its potential involvement in cancer-related processes." (PMID 33371395, 2020). "Overall, these findings underscore the multifaceted role of LINC00518 as a crucial regulator in various cancer types, highlighting its potential as a biomarker and therapeutic target." (PMID 39108268, 2024). "In summary, LINC00518 plays a significant role in enhancing cancer cell motility and promoting cancer metastasis." (PMID 39108268, 2024). "The competitive endogenous RNA (ceRNA) regulatory network represents a key mechanism through which LINC00518 operates in cancer development." (PMID 39108268, 2024). "Meanwhile, miR-216b-5p was bound by SNHG1 and LINC00518 which has been shown to regulate cancer cells chemoresistance." (PMID 35152275, 2022). "Through the TCGA database, we found that compared with normal lung tissues, the expression of Linc00518 in cancer tissues of LUAD patients was significantly increased." (PMID 33937054, 2021). "Moreover, as chemotherapy constitutes one of the three pillars of cancer treatment, LINC00518’s role in radioresistance has also been explored." (PMID 39108268, 2024). "Since its initial discovery, extensive research has reported that LINC00518 can regulate various cancer-related phenomena, including cell cycle regulation, proliferation, migration, invasion, epithelial-mesenchymal transition (EMT), radioresistance, and drug resistance." (PMID 39108268, 2024). "These roles underscore LINC00518’s potential as a therapeutic target in cancer." (PMID 39108268, 2024). "The results obtained suggest that LINC00518, under potential transcriptional control by MITF, regulates an RNA–RNA network promoting cancer-related processes (i.e., cell proliferation and migration)." (PMID 33371395, 2020). "Long intergenic nonprotein coding RNA 518 (LINC00518), mapped to chromosome 6, has been shown to be upregulated and promote cancer cell growth and metastasis in breast and cervical cancer." (PMID 31712557, 2019).
LINC00518 also shares sentences with these, for which no sentence is quoted: colon cancer (1 paper); gastric cancer (1); lung carcinoma (1); non-small cell lung carcinoma (1); ovarian carcinoma (1); pancreatic cancer (1).